ARV1 (ARV1 fatty acid homeostasis modulator)
Description:
Plays a role as a mediator in the endoplasmic reticulum (ER) cholesterol and bile acid homeostasis. Participates in sterol transport out of the ER and distribution into plasma membranes.
Synonyms: DEE38; EIEE38
Tractability: Antibody: UniProt predicts a signal peptide or a membrane-spanning region. PROTAC: ubiquitination databases record sites on it.
Gene: Protein-coding gene on chromosome 1 (230,978,981 to 231,000,733, forward strand). Ensembl gene ENSG00000173409.
Subcellular location: Endoplasmic reticulum membrane
Subcellular location (Human Protein Atlas): Vesicles
Pathways (Reactome):
Metabolism: Cholesterol biosynthesis
Gene Ontology:
Molecular function: protein binding; sterol transfer activity
Biological process: cholesterol transport; regulation of cholesterol metabolic process; regulation of intracellular cholesterol transport; cholesterol biosynthetic process; GPI anchor biosynthetic process; intracellular sterol transport
Cellular component: endoplasmic reticulum membrane; endoplasmic reticulum
Genetic constraint (gnomAD): Loss-of-function variants: 24 observed, 29.85 expected, observed/expected ratio (o/e) 0.8, 90% interval 0.58 to 1.13. The upper end of that interval is the gene's LOEUF score, 1.13, which puts it in group 4 of 6, group 1 being the genes least tolerant of losing a copy. Missense variants: 254 observed, 304.29 expected, observed/expected ratio (o/e) 0.83, 90% interval 0.75 to 0.93. Synonymous variants: 107 observed, 118.88 expected, observed/expected ratio (o/e) 0.9, 90% interval 0.77 to 1.06.
Homologues: Orthologues: chimpanzee ARV1 (99% identical), macaque ARV1 (97% identical), rabbit ARV1 (89% identical), dog ARV1 (89% identical), pig ARV1 (87% identical), guinea pig ARV1 (79% identical), mouse Arv1 (79% identical), rat Arv1 (70% identical), tropical clawed frog arv1 (62% identical), zebrafish arv1 (54% identical), Caenorhabditis elegans arv-1 (22% identical), Drosophila melanogaster Arv1 (21% identical).
Diseases named in the same sentence as ARV1 in open-access papers:
ARV1 is named in the same sentence as 26 diseases in open-access papers, as found by Europe PMC text mining. Sharing a sentence is not in itself a finding about the gene and the disease. The quoted sentences say what the papers report.
developmental delays (3 papers, 2022 to 2025). "A case report in 2017 described two siblings with severe developmental delays, generalised hypotonia, and early-onset epilepsy caused by ARV1 mutations." (PMID 40376369, 2025). "In this case report, we present a novel homozygous three-base-pair deletion leading to loss of one amino acid in ARV1 (c.554_556delTAT, p.L185del) in a 21-year-old man with developmental delay, ID, seizures, walking and speech impairments, and DCM." (PMID 35227294, 2022).
cognitive disorder (2 papers, 2019 to 2025). A disease affects cognitive processes. "Interestingly, an ARV1 variant harboring a Cys34 to Tyr mutation, which is within this ADD domain, has been linked to epileptic encephalitis and cognitive disorders." (PMID 39952408, 2025).
epilepsy (2 papers, 2025). A brain disorder characterized by episodes of abnormally increased neuronal discharge resulting in transient episodes of sensory or motor neurological dysfunction, or psychic dysfunction. "Dysfunction or mutations in the ARV1 gene can lead to severe metabolic disorders and have been linked to conditions such as congenital disorders of glycosylation and epilepsy." (PMID 40416165, 2025). "By sharing these cases, we’re adding to the growing knowledge about ARV1-related encephalopathies and reinforcing why this gene deserves a place in targeted epilepsy genetic panels." (PMID 40416165, 2025).
co-infection (1 paper, 2024). "The first identified ARV-1 in Slovenia (the sample named 341/2019) was detected in an affected honeybee colony as a co-infection, together with three other honeybee viruses (CBPV, DWV-A, DWV-B)." (PMID 39590430, 2024).
dilated cardiomyopathy (1 paper, 2022). Cardiomyopathy which is characterized by dilation and contractile dysfunction of the left and right ventricles. "The finding of dilated cardiomyopathy in the presented as well as in three previously reported patients from two different families indicates that dilated cardiomyopathy is a part of the ARV1-induced DEE38 phenotype." (PMID 35227294, 2022).
Epileptic encephalopathy (1 paper, 2025). A condition in which epileptiform abnormalities are believed to contribute to the progressive disturbance in cerebral function. "These infants were found to possess ARV1 gene mutations through whole-exome sequencing, a known genetic cause of developmental and epileptic encephalopathy." (PMID 40416165, 2025).
fungal infection (1 paper, 2016). "Thus, there exists a link between Arv1 function, maintaining proper phosphatidylserine homeostasis, and fungal infection." (PMID 27587298, 2016). "Uncovering the motifs required for Arv1 function will help to understand the molecular basis for Arv1-driven virulence, while further underscoring the importance of maintaining proper lipid distribution during fungal infection." (PMID 27587298, 2016).
Insulin resistance (1 paper, 2015). Increased resistance towards insulin, that is, diminished effectiveness of insulin in reducing blood glucose levels. "A better understanding of ARV1 and its downstream effectors may identify new targets for the treatment of obesity and insulin resistance in humans." (PMID 26479315, 2015).
lipodystrophy (1 paper, 2015). A congenital or acquired disorder characterized by abnormal loss or redistribution of the adipose tissue in the body. "The global decrease in WAT in the Arv1 KO mice is best described as a lean phenotype, as it was not accompanied by other features of congenital lipodystrophy." (PMID 26479315, 2015).
pancreatic cancer (1 paper, 2018). "Our results suggest that GT3 targets ceramide synthesis and transport, and that the upregulation of ceramide and modulation of transporters CERT and ARV1 are important contributors to the apoptotic properties demonstrated by GT3 in pancreatic cancer cells." (PMID 29769046, 2018). "Ceramide transporter CERT is downregulated and ER-localized sterol transport protein ARV1 is upregulated by GT3 in MIA PaCa-2, BxPC3, and Panc1 pancreatic cancer cells." (PMID 29769046, 2018). "However, this set of finely orchestrated events that may obviate the aberrant survival mechanisms present in pancreatic cancer cells, would not be functional without the upregulation of ARV-1 and downregulation of CERT." (PMID 29769046, 2018).
systemic candidiasis (1 paper, 2016). "Thus, targeting Arv1 for drug discovery may represent a novel approach for treating systemic candidiasis." (PMID 27587298, 2016).
tumor (1 paper, 2017). "Expression of ARV1 and ARV7 was measured in tumor tissue by quantitative RT-PCR, showing that expression of both variants was significantly increased in CR tumors compared to intact tumors." (PMID 28077788, 2017). "Unlike ARV7-expressing LNCaP xenografts, ARV1-expressing LNCaP xenografts were not significantly larger than control xenografts in pre-castrated mice, indicating that ARV1 does not promote tumor growth in vivo." (PMID 28077788, 2017). "In contrast to ARV7, ARV1 expression levels in tumor tissue from prostatectomy patients were not predictive of PSA recurrence." (PMID 28077788, 2017).
ARV1 also shares sentences with these, for which no sentence is quoted: developmental and epileptic encephalopathy (2 papers); infantile epileptic encephalopathy (2); Ataxia (1); Brain atrophy (1); carcinoma (1); cardiomyopathy (1); colorectal cancer (1); Dystonia (1); encephalopathies (1); Intellectual disability (1); neurogenetic disease (1); neurological diseases (1); Obesity (1); prostate tumors (1).